LUM (lumican)
Diseases named in the same sentence as LUM in open-access papers (continued):
Sharing a sentence is not in itself a finding about the gene and the disease.
tumor (continued). "However, the impact of LUM on neuronal tumor cell migration has not been investigated to date." (PMID 31861249, 2019). "As for tumor cell-blocks, none of the 10 AdC as well as the 3 NSCLC-NOS ones showed lumican immunoreaction, in accordance with the low expression detected in the resected specimens." (PMID 25961303, 2015). "Additionally, bone metastasis of the tumor, but not lung metastasis, was delayed in the NOD-SCID mice injected with the A549/luc BM 2nd cells after lumican downregulation." (PMID 31963522, 2020).
cancer (121 papers, 2007 to 2025). A tumor composed of atypical neoplastic, often pleomorphic cells that invade other tissues. "Assessment of the association between LUM expressions and four immunosuppressive cells in 33 human cancers revealed that LUM expressions were positively correlated with CAFs in almost all tumors." (PMID 37692065, 2023). "On the other hand, LUM is an extracellular matrix protein associated with signal transduction in cancer cells and can have either pro- or anti-tumorigenic effects in different cancer types." (PMID 37446304, 2023). "The link of the mRNA-miRNA-lncRNA-associated ceRNA network to several human cancers was established to develop a ceRNA network involving LUM in STAD." (PMID 38129820, 2023). "LUM expressions were cancer type-dependently differentially associated with chemotherapeutic responses." (PMID 37692065, 2023). "In various cancer cell lines, elevated LUM expressions were associated with decreased sensitivity to AICAR (an AMPK activator)." (PMID 37692065, 2023). "Lumican expression is associated with various cancer types, resulting in either protumorigenic or antitumorigenic effects." (PMID 36361971, 2022). "In human colon adenocarcinoma cells, lumican overexpression was found to be accompanied by changes in the actin polymerization state, immediately associated with cancer cells migration and higher metastatic potential." (PMID 34572532, 2021). "On the other hand, the expression of lumican and versican by cancer-associated fibroblastswas associated with a poor relapse-free and overall survival of esophageal squamous cell carcinoma." (PMID 34572532, 2021). "For instance, lumican was shown to be overexpressed in lung cancer cells and has been implicated in the pathogenesis of tumorigenesis and regulation of cancer cell invasion." (PMID 34638415, 2021). "This reduced expression of vinculin in the presence of lumican in the highly metastatic Snail-B16F1 cells underlines the anti-cancer action of lumican." (PMID 33917849, 2021). "Cluster 0 cells showed fibroblast signatures (RGS5 and NDUFA4L2), cluster 2 cells had strong expression of cancer associated fibroblast (CAF) markers (LUM, SFRP4, and COL1A1), and cluster 5 cells expressed myofibroblast markers (MYH11, TAGLN, and ACTA2)." (PMID 33662621, 2021). "Lumican, a small leucine-rich proteoglycan the down-regulation of which has been associated with lung invasion in different cancer types, was significantly inhibited at the mRNA level upon MG stress." (PMID 30674353, 2019). "Lumican and versican are proteins relevant to the biology of cancer and their expression was found to be associated with clinical outcome." (PMID 28481899, 2017). "A previous study by our group revealed that the presence of lumican in cancer cells was associated with a longer disease-free survival for stage II CRC patients." (PMID 28481899, 2017). "Among the genes that were upregulated in carcinomas, several well known stroma-associated glycoproteins were present, including lumican and versican." (PMID 28481899, 2017). "Given the varying clinical associations with lumican in several cancer types, more research is needed to determine the precise role of lumican in EOC." (PMID 26579497, 2015). "We further explored the specific mutation type and site of LUM among cancers." (PMID 38129820, 2023). "Abnormal LUM expression is potentially associated with cancer progression." (PMID 33493133, 2021). "Our data might thus indicate that the effects of lumican on the invasiveness of cancer cells were associated with p120ctn-mediated Rho family signaling." (PMID 29549325, 2018). "Importantly, in the HIF1A-knockout HepG2 cells, our qRT-PCR data confirmed the selected mRNA changes revealed by RNA-sequencing, and with TCGA pan-cancer data, we revealed that the expressional levels of these three genes, LUM, SCOC, and CCL2, were associated with immune cell infiltration levels." (PMID 35774500, 2022).
cancer (continued). "Similarly to decorin, lumican can also regulate cancer associated angiogenesis." (PMID 26056582, 2014). "P-selectin, β-2 microglobulin, ICAM-1, and lumican have been extensively investigated in relation to various types of cancer [,38]." (PMID 41031136, 2025). "The relationship between ICAM-1 and lumican and cancer appears to be variable, depending on the specific type and stage of cancer [,38]." (PMID 41031136, 2025). "LUM, a small proteoglycan family protein, binds collagen, and exhibits pathway dysregulation in many cancers." (PMID 40034439, 2025). "Members of the SLRP family (mainly biglycan, lumican, and decorin) modulate cancer cell functions such as proliferation, migration, adhesion, and invasion in several cancer types." (PMID 39334952, 2024). "The genes COL1A2, FSTL1, LUM, and SPARC encode proteins that structurally compose the ECM and that are frequently altered in cancer, conferring a poor prognosis and invasive phenotypes." (PMID 39563861, 2024). "In the W2 cluster, DEGs include POSTN, MFAP4, DCN, and LUM, which are closely involved in extracellular matrix organization as well as in cancer invasiveness." (PMID 39190696, 2024). "LUM was presented in the reactive stroma surrounding prostate primary tumors and played a restrictive role on cancer progression." (PMID 38459501, 2024). "KEGG analysis and GSEA enrichment analysis depicted that the genes co-expressed with LUM were enriched in several cancer-related pathways." (PMID 38129820, 2023). "In conclusion, LUM has different roles in different tumors, and this heterogeneity seriously affects our overall understanding of LUM, so this study performed a pan-cancer analysis of LUM to explore the overall trend of LUM." (PMID 37692065, 2023). "Over-expressed LUM has been found in various cancers, including BRCA, COAD, GBM, HNSC, PAAD, and STAD, in accordance with previous findings." (PMID 37692065, 2023). "To further validate the prognostic value of LUM in pan-cancer, we performed survival analysis on multiple datasets using the PrognoScan database." (PMID 37692065, 2023). "Biological function enrichment analyses suggested that the genes related to LUM expression were involved in extracellular matrix development-related pathways and enriched in several cancer-related pathways." (PMID 38129820, 2023). "On the other hand, LUM enhances cancer cell sensitivity to chemotherapeutic agents by inhibiting cell metabolism." (PMID 37692065, 2023). "The GSEA enrichment analysis revealed that LUM was involved in the regulation of many cancer metabolics and cancer immune signaling pathways." (PMID 38129820, 2023). "With regards to growth and metastasis, LUM plays a dual regulatory role in several cancer types, however, the specific mechanisms have yet to be established." (PMID 37692065, 2023). "Biologically, LUM inhibits or enhances cancer cell growth, differentiation, migration or metastasis by regulating growth receptors and signaling pathways." (PMID 37692065, 2023). "This review will focus on the functions of the class I and II SLRP members biglycan and lumican, which are correlated to various aspects of cancer development." (PMID 37509212, 2023). "In uterine CC tissues, LUM was expressed in most cancer cells and stromal fibroblasts, indicating its roles in the growth or invasion of CC." (PMID 36683048, 2023). "Lumican was proven to increase tumorigenesis in vivo, as well as cancer cell migration, invasion, and proliferation in vitro." (PMID 36361971, 2022). "The predicted target of compound 91b1 Lumican was found to be overexpressed in many kinds of cancer cells, and induced cancer cell migration and invasion." (PMID 36361971, 2022). "In cancer, lumican responds in a tissue-specific manner, both inhibiting cancer proliferation in melanoma and pancreatic, breast and prostate cancers while inducing growth and metastasis in lung and gastric cancers." (PMID 34982945, 2022).
cancer (continued). "The prior finding that high LUM expression around tumors is protective against metastasis in several cancer subtypes indicates the potential for LUM as a cancer-stalling therapy." (PMID 36873459, 2022). "Significantly enriched KEGG pathways, such as proteoglycans in cancer (DCN, LUM, WNT2B, HSPG2; p = 3.60e 04), were also mainly associated with downregulated proteins." (PMID 35340765, 2022). "eCAFs also strongly expressed cancer-associated genes including tumorigenesis SFRP2 (Secreted frizzled-related protein 2) and proteoglycan LUM (Lumican)." (PMID 35742914, 2022). "Overall, LUM expression by cancer cells seems to correlate with more aggressive cancers and poorer patient outcomes." (PMID 36873459, 2022). "The expression of lumican has been correlated with prognosis and disease stage in various cancer types." (PMID 34572532, 2021). "All these studies indicate that LUM plays critical roles in the progress and migration of right-sided cancers via ECM remodeling." (PMID 34590603, 2021). "Downregulation of the lumican expression attenuated lung osteotropic cancer cell’s adhesion to various ECM components, ultimately decreasing these cells’ migration." (PMID 34572532, 2021). "Scanning electron and confocal microscopy investigations demonstrated that lumican inhibits the development of elongated cancer cell phenotypes which are known to develop invadopodia releasing MMPs." (PMID 33917849, 2021). "We found that LUM cultivated cancer progression by targeting the miR200 family to promote epithelial-to-mesenchymal transition." (PMID 33493133, 2021). "Based on the available data and in a cancer-type specific manner, lumican roles as anticancer agents have been proposed." (PMID 34572532, 2021). "Investigating the role of LUM is a critical field of research in cancer molecular biology because it affects MMP regulation and has been demonstrated to inhibit MMP9 and MMP14 expression." (PMID 34310653, 2021). "Here, the effects of lumican on cancer cell growth, invasion, motility, and metastasis are discussed, as well as the repercussions on autophagy and apoptosis." (PMID 34572532, 2021). "Cancer‐associated fibroblasts (CAFs), expressing extracellular matrix (ECM) genes such as COL1A1, LUM, and BGN, formed the larger cluster." (PMID 33332768, 2020). "Biglycan, lumican, and fibromodulin are overexpressed in various types of cancer, whilst decorin is overexpressed in some types of cancer and suppressed in others." (PMID 33202923, 2020). "Reduction in the expression of lumican also decreased the attachment of lung osteotropic cancer cells to several components of the ECM and suppressed cell migration and invasion in vitro." (PMID 31963522, 2020). "Lumican was shown to influence cell function through various mechanisms in a tissue-specific manner in different cancers." (PMID 31406961, 2019). "The SLRP family member lumican (LUM) has been described to both positively and negatively regulate the metastatic potential of different cancers." (PMID 31861249, 2019). "It is thus currently somewhat unclear that what role lumican plays in the invasiveness and metastasis of cancer cells in general." (PMID 29549325, 2018). "We found that a functional effect of lumican on cancer cell invasion occurs via the physical interaction of tubulin and p120ctn." (PMID 29549325, 2018). "Lumican alters cancer progression by suppressing proliferation, migration, and invasion as well as upregulating epithelial markers and downregulating mesenchymal markers in an ER-independent fashion." (PMID 29881724, 2018). "The expression of LUM was only observed in the stroma of some types of cancer, whereas in others, we observed moderate to strong reactions in both the stroma and cancer cells." (PMID 29088800, 2017). "When considering the cancer subtype-specific homeobox genes, three genes were unique to LUM CSC, 6 to HER2-E CSC, and 21 to TN CSC." (PMID 28202042, 2017).
cancer (continued). "In lung adenocarcinoma (ADC) and squamous cell carcinoma (SCC), the expression pattern and glycosylated form of LUM in cancer cells and in stromal tissue correlated with the aggressiveness of ADC and SCC." (PMID 29088800, 2017). "In lung ADC and SCC, the expression of LUM was observed both in cancer cells and in stroma, although their levels of expression and their correlation to clinical data were different." (PMID 29088800, 2017). "Regarding lumican, it has been shown to variously modulate proliferation, migration and adhesion of cancer cells." (PMID 26056582, 2014). "It is of note that previous studies also observed the strong presence of lumican and versican in cancer cells." (PMID 22132114, 2011). "Increased expression of periostin and lumican was observed in carcinoma as well as in stromal cell in the large majority of cases." (PMID 24281036, 2010). "Cancer-associated fibroblasts (78 cells; cluster 13) specifically expressed COL1A2, DCN, and LUM." (PMID 40102789, 2025). "For example, the stromal subset consisted of endothelial cells identified by expressions of VWF, PECAM1 and KDR, pericytes with high RGS5, ACTA2, and COL4A1 expressions, and cancer-associated fibroblasts (CAFs) identified by significant expressions of COL1A1, DCN and LUM." (PMID 38925650, 2024). "In conclusion, LUM is a potential therapeutic target for cancer." (PMID 37692065, 2023). "Our findings elucidate on the significance of LUM in cancer therapy." (PMID 37692065, 2023). "The potential mechanism by which LUM influences cancer development and progression is complex and unknown." (PMID 38129820, 2023). "Our findings imply that LUM is a potential prognostic factor for cancers." (PMID 37692065, 2023). "Notably, SLRP class II member-LUM remains controversial in its anti-cancer effect and prognosis evaluation." (PMID 36816033, 2023). "In most tumors, differentially expressed LUM have been observed in cancer and normal tissues." (PMID 37692065, 2023). "Yet another small leucine-rich proteoglycan, lumican, regulates a host of physiological and disease processes, including fibrocyte differentiation, wound healing, glucose homeostasis, inflammation, cell migration, cancer and angiogenesis." (PMID 34982945, 2022). "This fact may in turn account for the relationship between p120 catenin or lumican expression in cancer and increased invasiveness, elevated cancer dissemination, and poor patient outcome." (PMID 35660718, 2022). "Downregulation of Lumican suppresses cancer cell migration and invasion in vitro." (PMID 36361971, 2022). "It is hypothesized that compound 91b1 inhibits cancer cell progression by downregulating Lumican expression." (PMID 36361971, 2022). "LUM may behave as an oncogene or tumor suppressor gene in several types of cancer, depending on the cellular context." (PMID 33493133, 2021). "Therefore, an in-depth study of the utilized mechanisms is imminent in order to identify the genotypic phenotype of lumican-responsive cancer to develop target therapeutic strategies." (PMID 34572532, 2021). "More specifically, immunohistochemistry demonstrated a much higher expression of lumican in cancerous gastric tissues than normal tissues.In this cancer type, the lumican expression was correlated with histological classification, cancer dissemination to secondary sites, and lymphatic metastasis." (PMID 34572532, 2021). "Very similar is the role of lumican, keratan sulfate, in cancer." (PMID 33917061, 2021). "Finally, in light of the available data, novel roles for lumican as a cancer prognosis marker, chemoresistance regulator, and cancer therapy target are proposed." (PMID 34572532, 2021). "However, the role of lumican in cancer is controversial and in many cases it actually facilitates cancer growth." (PMID 32548117, 2020). "Lumican is a member of the small leucine-rich proteoglycan family, and it has been identified to undergo overexpression or negative regulation in different types of cancer." (PMID 31437251, 2019).